IL6 (interleukin 6)
Diseases named in the same sentence as IL6 in open-access papers (continued):
Sharing a sentence is not in itself a finding about the gene and the disease.
tumor (continued). "In our work, we found that the stromal-derived SASP-factor IL-6 establishes myeloid-driven immunosuppression where CD8+ T cells were inhibited, resulting in unrestrained tumour growth." (PMID 27272654, 2016). "Taken together, our results suggested that deletion of IL6 promoted HCC development and increased tumor burden, NK cells, TNFα and IFNγ were significantly reduced in tumors of DDB1F/F, Alb-Cre+/−, IL6−/− mouse." (PMID 27556180, 2016). "The overexpression of IL-6 in PTC patients was significantly and linearly correlated with larger tumour size, presence of capsular invasion, and extrathyroidal extension of tumours." (PMID 27034885, 2016). "Interleukin 6 (IL6)-type cytokines such as oncostatin M (OSM) are key players in the regulation of the immune response, the immune surveillance of tumor cells, and in the development of cancer." (PMID 26889381, 2016). "Despite similar methods of activation and similar ratios of CD4 to CD8 T cells, we observed almost a ten-fold difference in TNF-α, IL-6 and IFN-γ released from F9 T cells compared to F38 T cells in response to tumor cells 24JKERB." (PMID 27153556, 2016). "To study the mechanism underlying this effect of the C-terminal domain, we analyzed expression of the cytokines, VEGF-A, interleukin 6 (IL-6), and tumor necrosis factor alpha (TNF-α), key genes for tumor growth, by RT-PCR." (PMID 28008951, 2016). "Since MMP14 is an activator of MMP2 and MMP9, a possible mechanism driving tumor invasion and migration is the activation of MMP2 and MMP9 through IL-6 induced MMP14." (PMID 27613828, 2016). "Enhanced S1PR1 upregulated the expression of IL-6, a pro-inflammatory cytokine crucial for STAT3 activation, inflammatory cell-mediated transformation, and tumor progression." (PMID 27129720, 2016). "Cachexia is believed to be induced by tumour-derived factors, such as tumour necrosis factor-α (TNF-α) and interleukin (IL)-6 (refs 9, 10)." (PMID 27538380, 2016). "The mechanisms how IL-22 confers stemness in tumor cells compared with other pro-tumorigenic cytokines also signaling through STAT3, such as IL-6 and IL-11, warrant further investigation." (PMID 27148488, 2016). "The genetic and epigenetic alterations acquired by carcinoma cells during primary tumor formation are likely to increase their responsiveness to various contextual signals such as TGF-β, TNF-α, IL-6 and EGF." (PMID 26909601, 2016). "Depending on the cell type, the IL-6/STAT3-dependent pathways, such as the JAK/STAT, PI3K/AKT/NF-κB, or p38 MAPK, can enhance tumor growth and refractoriness to chemotherapy." (PMID 26762586, 2016). "On the other hand, IL-17 increases the level of IL-6 and IL-8 in NSCLC cell lines and activates the STAT3 signaling pathway, mediating tumor angiogenesis." (PMID 27445423, 2016). "We demonstrated that ECs promote proliferation of tumor cells through releasing a combination of selective angiogenic factors, such as FGF2, IGF-1, IL-8, IL-6, and SDF1." (PMID 26762853, 2016). "Immune cells that infiltrate the tumour, excluding NK cells, produce tumour cytokine promoters, such as tumour necrosis factor alpha [TNF-α] and interleukins IL-1β, IL-6, and IL-8, which increase signalling in pre-malignant cells." (PMID 26913068, 2016). "IL-6, IL-8 and VEGF mRNA levels were increased by 2.3-, 4.1-, and 1.3-fold, respectively, in the tumour tissues of the A549-IL-17 cell-bearing nude mice compared with the mRNA levels in the controls." (PMID 27819281, 2016). "IL-6 primarily stimulates pro-inflammatory pathways, notably JAK/STAT signaling, which exerts several potentially tumor-promoting effects, including angiogenesis and enhanced invasive capacity." (PMID 27738330, 2016). "This is due to the secretion of the epidermal growth factor (EGF), platelet-derived growth factor (PDGF), TGF-β, IL-6, IL-1, and tumor necrosis factor (TNF)-α of TAMs, which creates a favorable milieu for tumor growth." (PMID 27044404, 2016).
tumor (continued). "Previous studies indicated IL6 and leukemia inhibitory factor (LIF) secretion increases in tumor tissues can promote TAM generation." (PMID 26790618, 2016). "Lee H used B16 cells, which have relatively low STAT3 activity and IL-6 expression in cell culture but greatly enhanced STAT3 activity in vivo, achieved at least in part through IL-6 production by the tumor stromal immune cells." (PMID 27129720, 2016). "In multivariate analysis of IL-6 expressions according to TNM staging (stage 0–stage 4) and grade of tumor in the GAC group, the median test was evaluated." (PMID 27196487, 2016). "IL-6, specifically, is a pro-inflammatory cytokine known to alter stromal cell function, migration, and EMT in the tumor microenvironment." (PMID 27515302, 2016). "IL16, produced by CD8+T cells, can stimulate the secretion of tumor-related cytokines, such as TNF-α, IL1β, IL6, and IL1516." (PMID 27703190, 2016). "Direct co-culture of tumor cells and macrophages shows that various factors secreted by activated macrophages, including IL-6, activate STAT3 in tumor cells." (PMID 27793010, 2016). "Although certain mechanisms governing cross talk between microenvironment and tumor cells have been previously elucidated, the role of pro-inflammatory cytokines, such as TNF, IL-6, and IL-1, is not completely understood." (PMID 27148266, 2016). "In a parallel experiment, sera of mice bearing either 4T1 tumours or CT26 tumours after different treatments were collected at 24, 72 and 168 h to analyse the changes of various cytokines including IL-6, TNF-α and IL-12p70." (PMID 27767031, 2016). "Increased IL-6 concentrations were shown to correlate with MDSC frequencies and their suppressive functions in tumor-bearing hosts." (PMID 27827871, 2016). "But AEG-1 overexpression did induce macrophages to produce crucial inflammatory factors such as IL-6 and TNF-α who are important in promoting tumor progression, invasion and metastasis." (PMID 27793010, 2016). "In a feedback loop, the hoisted B7-H3 and B7-H4 promoted T cells to secrete immunosuppressive cytokines IL-2, IL-6, IL-17, and TGF-β1, to maintain a tumor microenvironment." (PMID 27626488, 2016). "Functional analysis of tumor microenvironment revealed a correlation between CCL5 levels and IL-6 levels." (PMID 26759169, 2016). "Tumor markers SCCAg and CYFRA 21.1, cytokines IL-6 and VEGF, and soluble tumor necrosis factor receptors sTNFR I and II were evaluated as possible prognostic factors in all patients in the early stages of cancer development with a similar prognosis." (PMID 26289850, 2016). "Antibodies against human VEGF, IGF-1, FGF2, PDGF, TGF-β, IL-6, IL-8 and SDF-1 were individually added to primary human ECs conditional medium (phEC-CM) before treating tumor cells." (PMID 26762853, 2016). "We analyzed the serum levels of cytokines IL-6, IL-8, IL-10, IFN-γ, and TNF-α in tumor-bearing mice." (PMID 27764779, 2016). "Engagement of IL-6 with its receptor leads to activation of STAT3, which promotes the proliferation of cancer cells and tumor progression." (PMID 27148488, 2016). "This important finding defines a novel mechanism of PSC secreted IL-6 mediated activation of STAT3 signaling, as a critical regulator of tumor initiation and progression of PDAC." (PMID 27602757, 2016). "These multiple lines of evidence support the idea that pro-inflammatory stimuli, such as IL-1β, IL-6, IL-8 and TNF-α can lead to the activation of Notch signaling with a tumor-promoting effect on epithelial cells." (PMID 27929540, 2016). "To further evaluate the levels of microenvironmental IL-6 and cellular active PARP and Caspase-3, we performed immunohistochemistry (IHC) staining of tumor tissues." (PMID 27285760, 2016). "High levels of cytokines, including transforming growth factor beta (TGF-β), IL-6, IL-1 and TNF-α were produced during MM development in an in vivo mouse model by the MM cells and/or tumor infiltrating leukocytes." (PMID 27171110, 2016).
tumor (continued). "Anti‐IL‐6, and to a lesser degree anti‐IL‐17, led to attenuation of both lung and DLN micrometastases in 4THM tumor bearers." (PMID 26725371, 2016). "This study demonstrates a novel pathway of interaction between cancer cells and tumor promoting macrophages involving HDAC3 and IL-6." (PMID 26745602, 2016). "Conversely, TIS-CD8+ T cells promote CD16+ expression in monocytes/macrophages and the production of pro-inflammatory cytokines (TNF, IL-1β, and IL-6) and angiogenic factors (MMP-9, VEGF-A, and IL-8), which can affect tumor progression." (PMID 27129159, 2016). "GC-MSC share similar surface markers and the multi-differentiation potential with GCN-MSC, but secrete higher levels of several inflammatory cytokines, including IL-6, MCP-1, and VEGF, and have a stronger tumor-promoting ability." (PMID 26934326, 2016). "Dabigatran etexilate, with or without cisplatin, also reduced the levels of the proinflammatory cytokines MCP-1, IL-6 and IL-10 in the ascites of ID8 tumor bearing mice." (PMID 27852034, 2016). "Several proinflammatory cytokines, such as interleukin-1 (IL-1), IL-6, and TNF-a, expressed by the tumor environment induce CRP synthesis from the liver and other tissues." (PMID 26880857, 2016). "Lower levels of CEA, SCC, IL-6 and MIC-1 in the serum and C-myc and N-myc in tumours of CMSP-treated mice also indicated that xenograft cells exhibited a relatively benign phenotype." (PMID 27501997, 2016). "It is well established that pro-inflammatory cytokines and mediators, including IL-1β, IL-6, TNF-α, iNOS and Cox-2 which acts as tumor promoter is tightly modulated by transcription factor NFκB." (PMID 27563884, 2016). "Following a response to MAPK pathway inhibition, there is an increase in PD-L1 expression on tumor cells and a higher lymphocytic infiltration (CD8/CD4), as well as, a decrease in Treg infiltration and immunosuppressive cytokines (IL6, IL10, VEGF)." (PMID 27447748, 2016). "Cytokine profiling of the supernatants obtained from the irradiated tumor cells showed increased levels of VEGF, Rantes, PDGF, GMCSF and IL-2 and decreased levels of IL-6 and SCF." (PMID 27561007, 2016). "Ascophyllan treatment led to marked increases in the percentage of IL-6-, IL-12- and TNF-α-producing DCs in spleen of tumor-bearing mice." (PMID 27008707, 2016). "M1 macrophages produce large amounts of pro-inflammatory cytokines such as TNF-α, COX-2 and IL-6, which can generate NO and ROS and express high levels of MHC molecules functioning as killers of pathogens and tumour cells." (PMID 27907187, 2016). "Based on the elevated IL-6 levels in C3HBA tumors in Chy mice, both intracellularly and in the tumor interstitial fluid, we assessed the influence of the IL-6 receptor antibody tocilizumab on tumor growth." (PMID 27329584, 2016). "At the molecular level, impaired tumor growth in the three PDXs treated with p38 MAPK inhibitor correlates with downregulation of the chemokines CXCL-1 and CXCL-2 and the cytokine IL-6, which are all known to play key roles in colon tumorigenesis." (PMID 25890501, 2015). "Hypoxia represents a decisive stage in tumour progression, as the HIF1 transcription factor cooperates with the IL-6, TGF-β and VEGF factors in the promotion of tumour growth." (PMID 25932044, 2015). "The IL-6 pathway is aberrant in GBM, correlated with the degree of malignancy and supports cell proliferation, migration, tumor growth and GSC tumorigenesis." (PMID 26267319, 2015). "High levels of IL-6 in exhaled breath condensate (EBC) and in serum were confirmed to be related to tumor size in patients with NSCLC." (PMID 25504436, 2015). "The activation of macrophages facilitates the production of many immunomodulatory substances including cytokines, such as TNF-α, IL-6 and IFN-γ, which are known to play an important role in suppressing tumor cells." (PMID 26032186, 2015).
tumor (continued). "If on one side tumor cells secrete a plethora of factors such as TGF-β1, PDGF, VEGF, IL-6, FGF-2, IFN-γ, TNF, MMPs involved in fibroblast activation, on the other side CAFs produce the same molecules that in turn affect tumor aggressiveness." (PMID 25474039, 2015). "A week later, the tumor-bearing mice were treated with sunitinib, sunitinib in combination with IPA3 or sunitinib in combination with IL-6 neutralizing antibody." (PMID 25675297, 2015). "The aim of the present review is to address the role of ghrelin, myostatin, leptin, HIF, IL-6, TNF-α, and ANGPTL-4 in the regulation of energy balance, tumour development, and tumoural cell invasion." (PMID 26508818, 2015). "Obese and visceral derived ASC, but not lean SC-ASC, increased expression of chemotactic factors IL-6, MIP-2, and MCP-1 when cultured with tumor cells." (PMID 26317219, 2015). "The cytokines IL-1β, IL-6, IL-8 and TGF-β play important roles in the development of drug resistance in tumor cells." (PMID 25950430, 2015). "After neutralizing IL-6 with a blocking mAb, IL-17 stimulation still significantly increased p-STAT3 expression in tumor cells even though STAT3 activation was diminished." (PMID 26524953, 2015). "Reported mechanisms include overexpression or mutations in PSMB5 (the proteasomal target of BTZ), P-glycoprotein expression (efflux pump), microenvironmental upregulation of IL-6, IGF-1, or tumor upregulation of HSP90, PI3K, MYC, and IGF-1." (PMID 26254279, 2015). "This took into account five clinical variables (gender, performance status, forced expiratory volume, number of lymph node stations and tumour volume), the performance of this model was improved upon the addition of two blood borne biomarkers CEA and IL-6." (PMID 26425690, 2015). "Interleukin-6 (IL-6) and tumor necrosis factor-α (TNF-α) are important proinflammatory cytokines produced by inflammatory cells as well as tumor cells." (PMID 26674205, 2015). "Various MMPs, inflammatory cytokines, chemokines and angiogenic factors, such as IL6, IL8, CXCL1, RANTES, and VEGF are secreted from tumor cells during EMT." (PMID 26084289, 2015). "In our study, GC-MSCs expressed higher levels of VEGF, MIP-2, TGF-β1, IL-6, and IL-8 than GCN-MSCs or BM-MSCs did, suggesting a more potent role of GC-MSCs in tumor angiogenesis." (PMID 25986392, 2015). "At the same time, miR-106a can also enhance the production of IL-1β, IL-6, IL-8 and TGF- β, and thus affect the tumor microenvironment to contribute to the development of drug resistance." (PMID 25950430, 2015). "In this study the circulating level of IL-6 was constant from one group to another, suggesting that TNF-α is more critical than IL-6 in tumor-induced muscle wasting." (PMID 25797259, 2015). "Cytokines such as IL-6 can promote an EMT and endow tumor cells with cancer stem cell properties, and TGFβ, which has well-established roles in the induction of EMT, can cooperate with TNF to induce EMT, stemness and tumorigenicity." (PMID 26207831, 2015). "Syngeneic graft assays again showed that YAP overexpression increased tumour-initiating cell frequency, and SRF or IL6 depletion decreased it." (PMID 26671411, 2015). "This assumption is supported by our in vitro HCC cell-line studies in which STC1 inhibited the pro-migratory effects of IL6 and IL8, and reduced sizes of tumor spheroids." (PMID 26469082, 2015). "IL-6 activates the JAK-STAT3 pathway, leading to increased tumor-infiltrating lymphocytes, which has been widely documented." (PMID 26684834, 2015). "IL-11 as well as IL-6 activates STAT3, which is closely related to growth, differentiation and metastasis of cancer cells in the tumour microenvironment." (PMID 28781374, 2015). "EB selectively inhibited constitutive as well as IL-6-induced phosphorylation of STAT3 and induced apoptosis of STAT3-dependent tumor cells." (PMID 26010889, 2015). "The IL-6 pathway is known to be aberrant in GBM and to promote cell proliferation, migration and tumor growth in vivo." (PMID 26267319, 2015).
tumor (continued). "Here, we also show that suppressing IL-6 with adjuvant siRNA blocks downstream production of VEGF and distant tumor angiogenesis, underscoring the potential utility of using adjuvant siRNA when the target is sufficiently upstream in the pathway." (PMID 26154425, 2015). "Abnormal signaling pathway activation, including AKT, IL-6/STAT3 and MAPK/ERK, is considered to be significant for the EMT, pro-tumorigenic inflammatory cytokine secretion, invasion and metastasis of tumor cells." (PMID 25788270, 2015). "In the tumor milieu, IL-1 induces expression of various metastatic mediators such as MMP, VEGF, IL-8, IL-6, TNFα, and TGFβ (reviewed in 9,13,30,31)." (PMID 26460957, 2015). "The 9 patients with a skin GvHD stage II and III, developed significant increases of IL-6 (P = 0.0010), sIL-2R (P = 0.0049) and TNF-α (P = 0.0020) in the serum, whereas IL-8, IL-10 and IL-1ß did not significantly change." (PMID 26315105, 2015). "We show that CCL2 is the main molecule produced in this DIO tumor model with chemotactic and tumor-promoting activities, followed by the chemokine IP-10 (CXCL10) and by the pro-tumor pro-inflammatory cytokine IL-6." (PMID 25599228, 2015). "Since VEGFA expression has been correlated with tumour invasiveness, and the presence of vaso-invasion negatively affects clinical outcome, blocking both IL-6 and VEGFA has the potential to counteract both tumour growth and invasion." (PMID 25889974, 2015). "The use of primary lung fibroblasts isolated from RhoB deficient transgenic mice allowed us to identify activation of 3 major proteins in the secretome of TC-1 tumor cells cultured with conditioned media produced by these fibroblasts: MMP, bFGF and IL-6." (PMID 25635683, 2015). "Several studies have found an increased expression of IL-6 in patients with CRC, where IL-6 levels are elevated in the serum of patients and in tumor tissue itself." (PMID 26258407, 2015). "Activated NF-κB in tumor cells results in high expressions of immunosuppressive factors such as IL-6, IL-10, TGF-β and VEGF, and impedes the anti-tumor immunity." (PMID 26683520, 2015). "Taken together, not only complementation with tumour-specific young CD4+ T cells, but IL-6 blockade that augmented IFN-γ production was also necessary for improvement of antitumour responses in aged mice." (PMID 25850032, 2015). "Dectin-1 engagement is apparent to up-regulate costimulatory molecules such as CD80, produce TNF-α, IL-6, IL-2, IL-10, IL-12, and IL-23, and elicit potent CTL responses that protect mice from tumor challenge." (PMID 26379663, 2015). "The aim of this study was to investigate the correlation of serum IL-6 and TNF-α levels on tumour recurrence in patients with OSCC in order to identify potential biomarkers for early detection of disease recurrence." (PMID 25858079, 2015). "Our data suggested that STC1 inhibited pro-migratory effects of IL6/IL8 and enable apoptotic pathways in tumor cells to reduce growth and metastasis of HCC." (PMID 26469082, 2015). "The aim of this study was to investigate the relationship of pretreatment serum IL-6 and TNF-α levels on tumour recurrence in patients with OSCC in order to identify potential biomarkers for the early detection of disease recurrence." (PMID 25858079, 2015). "Both IL-6 neutralizing antibody and IPA3 administration enhanced tumor growth inhibition effect of sunitinib treatment on RCC cells in vitro and in vivo." (PMID 25675297, 2015). "Pro inflammatory cytokines such as interleukin-6 (IL-6) and tumour necrosis factor alpha (TNF-α) have been suggested to play a certain role in the variety of tumours." (PMID 25858079, 2015). "This was associated with a transient expansion of myeloid cells and increased cytokines with myelogenic potential including C-C chemokine ligand 2 (CCL2), interleukin-6 (IL-6), and VEGF-A that primed the environment for tumor growth." (PMID 26459393, 2015).